FAM186B (family with sequence similarity 186 member B)
Synonyms: C12orf25; DKFZP434J0113
Tractability: No criterion of Open Targets' tractability assessment is met for any kind of drug.
Gene: Protein-coding gene on chromosome 12 (49,582,885 to 49,605,639, reverse strand). Ensembl gene ENSG00000135436.
Subcellular location (Human Protein Atlas): Cytosol; Nucleoplasm; Basal body; Centrosome
Gene Ontology:
Cellular component: protein-containing complex
Genetic constraint (gnomAD): Loss-of-function variants: 68 observed, 85.9 expected, observed/expected ratio (o/e) 0.79, 90% interval 0.65 to 0.97. The upper end of that interval is the gene's LOEUF score, 0.97, which puts it in group 4 of 6, group 1 being the genes least tolerant of losing a copy. Missense variants: 983 observed, 1,146.4 expected, observed/expected ratio (o/e) 0.86, 90% interval 0.81 to 0.9. Synonymous variants: 389 observed, 441.84 expected, observed/expected ratio (o/e) 0.88, 90% interval 0.81 to 0.96.
Homologues: Orthologues: chimpanzee FAM186B (98% identical), macaque FAM186B (94% identical), pig FAM186B (68% identical), dog FAM186B (64% identical), guinea pig FAM186B (63% identical), rat Fam186b (60% identical), mouse Fam186b (59% identical).
Diseases named in the same sentence as FAM186B in open-access papers:
FAM186B is named in the same sentence as 1 disease in open-access papers, as found by Europe PMC text mining. Sharing a sentence is not in itself a finding about the gene and the disease.
FAM186B shares sentences with these, for which no sentence is quoted: colon cancer (1 paper).